INS (insulin)
Diseases named in the same sentence as INS in open-access papers (continued):
Sharing a sentence is not in itself a finding about the gene and the disease.
type 1 diabetes (continued). "People with type 1 diabetes typically need to lower their insulin dose in connection with exercising due to the increase in insulin sensitivity." (PMID 40604313, 2024). "Type 1 diabetes results from damage to insulin-producing cells because of an autoimmune response, leading to a lack of insulin production." (PMID 39744344, 2024). "The American Diabetes Association (ADA) recommends physical activity for individuals with type 1 diabetes as it improves glycemic control, decreases insulin requirements, and reduces cardiovascular complications in individuals with type 1 diabetes." (PMID 38686202, 2024). "Type 1 diabetes (T1D) is a chronic autoimmune disorder characterised by an autoimmune response specifically mounted against the insulin-producing beta cells." (PMID 39682744, 2024). "A child with type 1 diabetes came off insulin completely after strictly following a low-carb paleolithic ketogenic diet." (PMID 37584373, 2023). "While these newer insulin preparations helped more people with type 1 diabetes achieve targeted glucose levels, further glycemic improvements required advancements in glucose monitoring technologies." (PMID 37794113, 2023). "This was the first clinical trial showing that 10 days of administration of alpha lipoic acid is able to manage insulin-stimulated glucose disposal in non-insulin-dependent diabetes mellitus." (PMID 37597078, 2023). "Proximal digital tools such as insulin pumps and continuous glucose monitoring devices have become more widespread in recent years to facilitate and improve the management of type 1 diabetes." (PMID 37004000, 2023). "Type 1 diabetes (T1D) is regarded to be an autoimmune disease where pancreatic islet β-cells, producing insulin, are destroyed." (PMID 37638044, 2023). "In the streptozotocin-induced type 1 diabetes model, decreased insulin levels is accompanied by a decrease in apelin levels." (PMID 37424869, 2023). "Type 1 diabetes (T1D) is an immune-mediated chronic disease in which insulin-producing β cells perish." (PMID 37079135, 2023). "In type 1 diabetes, patients are unable to produce insulin due to an autoimmune response to the body’s insulin-producing beta cells." (PMID 36771921, 2023). "One of the experiences expressed by several participants with type 1 diabetes, was the desire to control their insulin management during labour and delivery (described in a previous theme)." (PMID 37131168, 2023). "While the anti-DRiP1-13 antiserum specifically detected the INS-DRiP polypeptide recognised by cytolytic T cells in individuals with type 1 diabetes, the anti-SPLICE81-95 antiserum reacted with both recombinant INS-DRiP and INS-splice proteins." (PMID 36884057, 2023). "Hypoglycemia is the most common complication in type 1 diabetes patients and corresponds to an inadequacy between insulin substitution, insulin needs and carbohydrate intake with a consecutive drop of glycemia (i.e., below 60 mg/dL)." (PMID 38033011, 2023). "We aimed to investigate the effects of different insulin pump settings ontime in range in patients with type 1 diabetes during Ramadan." (PMID 34809475, 2023). "Diabetes Type-1 is characterized by an autoimmune attack on the pancreatic insulin-producing β cells, which leads to insufficient insulin synthesis." (PMID 37394484, 2023). "AiDAPT (automated insulin delivery amongst pregnant women with type 1 diabetes) is a multicenter randomized controlled trial, currently still in progress, whose aim is to evaluate the impact of AHCL during pregnancy in women with type 1 diabetes." (PMID 36983941, 2023). "A randomized controlled trial concludes that in patients with type 1 diabetes who receive multiple daily insulin injections, the use of CGM resulted in a significant decrease in HbA1c levels over 24 weeks compared to usual care." (PMID 37810892, 2023). "Usually, type 1 diabetes occurs under the age of 30, and patients are insulin-dependent, pumping insulin into their bodies." (PMID 36832207, 2023).
type 1 diabetes (continued). "Insulin deficiency, the most common type of canine diabetes, is characterized by the autoimmune destruction of pancreatic β-cells, which leads to insufficient insulin production and glucotoxicity comparable to that seen in human type 1 diabetes (T1DM)." (PMID 36865924, 2023). "Unlike type 1, which typically manifests in childhood or adolescence, T2DM (also known as "non-insulin-dependent diabetes") develops in adulthood and is characterized by the body's inefficient use of insulin (known medically as "peripheral tissue resistance")." (PMID 37346355, 2023). "Since type 1 diabetes is a chronic condition, it requires constant insulin replacement and intensive blood glucose level control by the patient." (PMID 37074460, 2023). "People with type 1 diabetes who are C-peptide positive experience less hypoglycemia than those who are negative for the protein and maintain robust glucagon responses to insulin-induced hypoglycemia." (PMID 37166980, 2023). "Type 1 diabetes (T1D) is an autoimmune disease culminating in the destruction of insulin-producing pancreatic cells." (PMID 37509587, 2023). "In conclusion, the present study supports the value of primary graft function in the management of type 1 diabetes patients undergoing beta-cell replacement with various modalities, such as PTx, ITx, or other insulin-secreting cell transplantation." (PMID 38213551, 2023). "In patients known to have type 1 diabetes, we recommend good glycemic control through strict appropriate insulin doses, periodic biochemical tests, balanced dietary plans, physical activity, and minimization of stress." (PMID 37185051, 2023). "In a UK centre, routine C-peptide testing of all adult-onset type 1 diabetes resulted in 11% of individuals being re-classified, with~25% of these individuals discontinuing insulin therapy." (PMID 37728732, 2023). "T1DM is also known as “insulin-dependent diabetes” due to the dependency of T1DM individuals on insulin shots to maintain blood glucose levels." (PMID 36835260, 2023). "We identified 196,691 individuals with type 1 diabetes, 13% of whom were treated with adjunctive glucose-lowering therapy in addition to insulin." (PMID 37505282, 2023). "We have previously identified INS-DRiP in type 1 diabetes immunopathology as target of cytolytic CTLs in individuals with type 1 diabetes." (PMID 36884057, 2023). "The aim of this study was to assess the safety and efficacy of the WJMSC drug product, ProTrans, in maintaining endogenous insulin production to slow the progression of type 1 diabetes." (PMID 37221247, 2023). "The future of insulin treatment in type 1 diabetes appears promising with AI, with research nearly reaching the possibility of finally having a “closed-loop” artificial pancreas." (PMID 37685946, 2023). "Type 1 diabetes mainly affects youngsters and is defined by an insulin shortage that necessitates daily insulin injections." (PMID 37624794, 2023). "In type 1 diabetes (T1D) insulin-producing beta cells are destroyed by the immune system and patients are dependent on life-long administration of exogenous insulin for glycemic control and survival." (PMID 37908676, 2023). "Type 1 diabetes is a condition diagnosed when the body produces insufficient insulin to function well." (PMID 37187938, 2023). "In type 1 diabetes, intensive insulin therapy that restores normal glycemic levels increases stimulated C-peptide levels, a reflection of improved insulin biosynthesis and preserved β cell function." (PMID 38032734, 2023). "Effective management of type 1 diabetes requires regular daily monitoring of blood glucose levels and adjusting the number of insulin doses." (PMID 38201852, 2023). "Type 1 diabetes (T1D) is predominantly the result of autoimmune-related injury to insulin-producing pancreatic islet β-cells of Langerhans." (PMID 37400916, 2023).
type 1 diabetes (continued). "Type 1 diabetes (T1D) is a chronic condition where the pancreas stops producing insulin and can in itself (or as a result of treatment) result in high or low glucose levels, both of which can constitute a medical emergency." (PMID 40303271, 2023). "The current mainstay of treatment for Type 1 Diabetes uses exogenous insulin administered either as intermittent injections multiple times a day, or through a continuous infusion pump." (PMID 37789914, 2023). "Thus, the decreased concentrations of leucine, as well as of other EAAs, following systemic hyperinsulinemia and, conversely their increase in the insulin-deficient condition of type-1 diabetes, could be positively related to concurrent changes in endogenous protein breakdown." (PMID 38201949, 2023). "Preproinsulin and insulin (or derivatives) are major antigenic targets of the human autoreactive T cell repertoire that infiltrate islets in type 1 diabetes." (PMID 37488322, 2023). "At the age of 15, the patient had a random blood glucose of 33.1 mmol/L, and was diagnosed with “type 1 diabetes, diabetic ketosis,” and was discharged after insulin treatment." (PMID 37974252, 2023). "The progressive autoimmune attack on pancreatic β-cells results in the loss of insulin secretion and production, ultimately affecting the blood sugar levels and metabolic functions resulting in a condition termed type 1 diabetes mellitus (T1D)." (PMID 37434264, 2023). "Refers to the selective transplantation of the islets of Langerhans, the parts with endocrine, i.e., insulin-producing, functionality in the definitive treatment of type I diabetes mellitus." (PMID 37503334, 2023). "Insulin-producing beta cells are found in the islets, and when these cells are damaged, humans develop type 1 diabetes (T1D)." (PMID 37650011, 2023). "Inclusions in the study were type 1 diabetes subjects with known age of onset, insulin-dependent for at least six months, and diagnosed between the ages of 6 and 16 years old." (PMID 36817429, 2023). "Studies of new therapies to preserve insulin secretion in early type 1 diabetes require several years to recruit eligible subjects and to see a treatment effect; thus, there is interest in alternative study designs to speed this process." (PMID 38096190, 2023). "Patients with type 1 diabetes must continually decide how much insulin to inject before each meal to maintain blood glucose levels within a healthy range." (PMID 37835893, 2023). "Type 1 diabetes (T1D) is an autoimmune disorder that destroys insulin-generating pancreatic β-cells." (PMID 38040681, 2023). "In this paper, we test and evaluate several deep Q-learning algorithms for automated and personalized blood glucose regulation in an in silico type 1 diabetes patient with the goal of estimating and delivering proper insulin doses." (PMID 37835893, 2023). "Type 1 diabetes (T1D) is an autoimmune disease that results from the destruction of insulin-secreting β-cells in the pancreatic islets of Langerhans by autoreactive CD4+ T cells upon recognition of one or more β-cell peptides." (PMID 37810138, 2023). "One prominent example is the UVa/Padova type 1 diabetes simulator that has been approved by the FDA for preclinical testing of control algorithms for insulin treatment." (PMID 36791144, 2023). "Type 1 diabetes, also known as juvenile diabetes or insulin-dependent diabetes, is a chronic autoimmune disease that occurs when the immune system attacks and destroys the insulin-producing beta cells in the pancreas." (PMID 37663700, 2023). "When insulin secretion is lost in type 1 diabetes, paracrine inhibition on the α-cells is disrupted, too much glucagon is released, and glucose levels are worsened due to glycogenolysis and gluconeogenesis." (PMID 37296593, 2023). "Twenty-four adults with insulin pump-treated type 1 diabetes (HbA1c ≤70 mmol/mol [8.5%]) completed a randomised, open-label, two-period crossover study with 2 week periods." (PMID 37037948, 2023).
type 1 diabetes (continued). "There is a 14-year-old patient, she is in the last trimester of her pregnancy and she is an insulin-dependent diabetic, she has type I diabetes..." (PMID 37930234, 2023). "Pancreatic beta-cell replacement therapy by clinical islet transplantation (CIT) has been shown to be a promising alternative to conventional insulin treatment used for type I diabetes." (PMID 37298999, 2023). "Insulin Infusion Sets (IIS) play a crucial role in ensuring the safe delivery of insulin through a Continuous Subcutaneous Insulin Infusion (CSII) for individuals with Type 1 Diabetes (T1D)." (PMID 38093983, 2023). "The improvement in glucose control was in line with that reported during and immediately after COVID-19 pandemic lockdown in people with type 1 diabetes or, less consistently, with T2D, particularly patients using insulin." (PMID 37663860, 2023). "Type 1 diabetes (T1D) is an autoimmune condition of children and adults in which immune cells target insulin-producing pancreatic β-cells for destruction." (PMID 37256143, 2023). "The efficacy of S‐300 WIM device in delivering insulin‐secreting cells for glycemic correction was evaluated in a chemically induced mouse model of type I diabetes." (PMID 37206238, 2023). "Patients with Type-1 diabetes rely on exogenous insulin delivery, which usually has two types, one is rapid-acting insulin named bolus and the second is slow-acting insulin termed basal insulin." (PMID 36766445, 2023). "This guideline summarizes diagnosis of type 1 diabetes, including accompanying autoimmune disorders, insulin therapy regimens and glycemic target values." (PMID 37101030, 2023). "Juvenile type 1 diabetes refers to insulin-dependence, and it occurs when the beta cells in the body cannot produce enough insulin." (PMID 36832207, 2023). "Type 1 diabetes (T1D) is a chronic autoimmune disease characterized by the destruction of insulin-producing pancreatic β-cells by the immune system." (PMID 38203514, 2023). "This is the first clinical trial aimed at comparing TH versus in-person visits among adults with type 1 diabetes treated with multiple insulin doses that includes a high percentage of participants using FGM." (PMID 37441496, 2023). "At the time of the centennial anniversary of the first clinical use of insulin, the treatment of type 1 diabetes has undergone multiple innovations that have advanced the health, well-being, and longevity of people living with the disease." (PMID 37794113, 2023). "Type 1 diabetes (T1D) is a CD4+ T cell-driven autoimmune disease characterized by the destruction of insulin-producing pancreatic β-cells by CD8+ T cells." (PMID 37226224, 2023). "T cell reactivity against pancreatic autoantigens is considered one of the main contributors to the destruction of insulin-producing cells in type 1 diabetes (T1D)." (PMID 36969220, 2023). "Treating type 1 diabetes mellitus (T1D) is a challenge for patients, their families, and multidisciplinary care teams due to the disease's characteristics, the use of insulin and the constant monitoring of blood glucose levels." (PMID 36748932, 2023). "Background and aims: Type 1 diabetes (T1D) is a chronic autoimmune disease characterized by a T-cell-mediated destruction of the pancreatic insulin-producing beta cells." (PMID 37174719, 2023). "New strategies for optimising maternal diet and insulin dosing from the first trimester are needed to improve pregnancy outcomes in type 1 diabetes." (PMID 37615689, 2023). "Type 1 diabetes is a chronic disease characterized by hyperglycemia, resulting from the progressive destruction of insulin-producing β-cells in the pancreatic islets of Langerhans." (PMID 37458220, 2023). "The main challenge in the treatment of type 1 diabetes is the complete automation of blood glucose control coupled with the automatic infusion of insulin, alone or together with glucagon." (PMID 37685946, 2023).
type 1 diabetes (continued). "Consistent with this, in studies of longstanding adult-onset type 1 diabetes defined by either low C-peptide or genetically, current clinical features, including BMI, HbA1c, insulin dose and ketoacidosis rates, were comparable irrespective of onset age." (PMID 37728732, 2023). "For example, insulin pumps, especially for patients with type 1 diabetes, require BG devices to be safe to ensure automated delivery of proper insulin dosage." (PMID 36917147, 2023). "Therapeutic strategies to maintain body mass within third centile of BMI-SDS ranges should be developed in order to prolong C-peptide, hence endogenous insulin secretion in new onset type 1 diabetes in children." (PMID 37180128, 2023). "Pancreatic transplantation restores insulin production in type 1 diabetes through the whole pancreas or islet cell transplant." (PMID 37965396, 2023). "One of the advantages of ViaCyte’s technology is the ability to provide a potential cure for type 1 diabetes by replacing the lost or damaged islet cells that produce insulin." (PMID 37965322, 2023). "From national registers, data were available on diagnosis or medication prescription for depression/anxiety in and around pregnancy, as well as incident cases of type 1 diabetes defined through diagnosis or insulin treatment." (PMID 37080595, 2023). "We aimed to characterize the microbiota in particular niches of the oral cavity in adult type 1 diabetes patients treated with continuous infusion of insulin with insulin pump (IP)." (PMID 36767617, 2023). "Type 1 diabetes is characterised by the progressive destruction of insulin-producing beta cells by CD8+ T cells." (PMID 37581620, 2023). "In type 1 diabetes, inadequate insulin secretion requires adherence to a lifesaving therapeutic regimen that includes blood glucose monitoring, multiple insulin administrations, carbohydrate counting, and regular physical activity." (PMID 36767985, 2023). "Type 1 diabetes is a chronic disease with a progressive dependence on exogenous insulin administration." (PMID 37297566, 2023). "LADA patients with high GAD titers will be more like patients with type 1 diabetes-for example, to be younger at diagnosis, have decreased BMI, and be more likely to progress to insulin." (PMID 37620783, 2023). "In this regard, type 1 diabetes (T1D) is a chronic disease that occurs when the pancreas is no longer able to produce enough insulin because of the autoimmune destruction of insulin-producing beta cells in the pancreas." (PMID 37835893, 2023). "Another example is type I diabetes, in which the B9-23 region of insulin initially sets off an autoimmune response, and the expansion of the epitope to a variety of beta cell antigens is what causes the manifestation of the disease." (PMID 36992490, 2023). "This review will summarize the development of insulin analogs, discuss the results of insulin trials in people with MDI-treated type 1 diabetes at increased risk of hypoglycemia, and compare these results with studies in people at low risk of hypoglycemia." (PMID 38089060, 2023). "This is clearly seen in the elevated levels of insulin and C-peptide in cord blood in pregnancies of women with type 1 diabetes." (PMID 36287249, 2023). "Experiencing stigma affects an alarmingly high percentage of people with type 1 diabetes, especially those who use intensive insulin therapy." (PMID 37570425, 2023). "It was also shown that golimumab, a monoclonal antibody against TNFα can have beneficial effects on endogenous insulin production and exogenous insulin requirements in children and young adults with newly diagnosed type 1 diabetes." (PMID 37180128, 2023). "The optimum method depends on the research question; for example, defining type 1 diabetes by low endogenous insulin precludes studying disease severity." (PMID 37728732, 2023). "Insulin has remained the cornerstone of treatment in type 1 diabetes since its discovery by Banting and Best in 1922." (PMID 37505282, 2023).